GALNT14 (polypeptide N-acetylgalactosaminyltransferase 14)
Diseases named in the same sentence as GALNT14 in open-access papers (continued):
Sharing a sentence is not in itself a finding about the gene and the disease.
cancer (33 papers, 2010 to 2025). A tumor composed of atypical neoplastic, often pleomorphic cells that invade other tissues. "Polypeptide N-acetylgalactosaminyltransferase 14 (GALNT14), a member of the N-acetylgalactosaminyltransferase family, has been considered to be associated with various cancers." (PMID 38024474, 2023). "The association between GALNT14 expression and cancer characteristics has been studied in multiple tumors." (PMID 38024474, 2023). "GALNT14 plays a role in glycosylation, and its association with the immune system can be inferred from its usefulness as a predictor in several cancers." (PMID 36140740, 2022). "The polypeptide N-Acetylgalactosaminyltransferase 14 (GALNT14) rs9679162 and mRNA expression were associated with treatment outcome in various cancers." (PMID 36077753, 2022). "Although rare, the identification of a recurrence of a GALNT14 mutation in NB adds evidence on an involvement of GalNAc-Ts in cancer generally, and in this pediatric neoplasia specifically." (PMID 26309160, 2015). "Notably, although no reports have specifically addressed this particular SNP, other genetic variations within the GALNT14 gene have demonstrated associations with diverse therapeutic responses in different cancers." (PMID 38928347, 2024). "Additionally, we observed that multiple cancer-related pathways were enriched through functional enrichment analysis of genes associated with GALNT14 levels, such as the Wnt, TGF-β, Hippo, and PI3K signaling pathways." (PMID 38024474, 2023). "Here, we showed upregulation of GALNT14 in CD82 restored metastatic prostate cells and it is uncertain whether adding CD82 caused methylation that increased GALNT14 expression in those cells, as seen in many cancers or is due to some other mechanism." (PMID 33298014, 2020). "Since GALNT14 enzyme levels have been associated with cancer characteristics, it can be speculated that GALNT14 enzyme expression levels are associated with different SNP genotypes." (PMID 32098271, 2020). "Regarding initiation of GalNAc-type O-glycosylation, GALNT2, GALNT3, GALNT6, GALNT7, and GALNT14 were highly expressed in both cancer types, LUAD and LUSC." (PMID 40718829, 2025). "Previous studies have suggested the significance of GALNT14 for the metastasis of a wide variety of cancers." (PMID 38024474, 2023). "In summary, previous reports have suggested abnormal expression of GALNT14 in cancer and metastatic tissues." (PMID 38024474, 2023). "GALNT14 has been expressed in multiple cancers altering several biological functions, and was recently described as an emerging marker capable of predicting outcomes." (PMID 37892181, 2023). "A slope of less than 0 indicates that GALNT14 mRNA expression is lower in cancer (T < N), and a slope greater than 0 indicates the opposite (T > N)." (PMID 36077753, 2022). "Polypeptide N-Acetylgalactosaminyltransferase 14 (GALNT14) has been identified as a putative driver of cancer metastasis, and predicts poor patient survival." (PMID 36110252, 2022). "In other cancers, GALNT14 has been shown to promote tumorigenesis or cancer progression by enhancing cell proliferation, migration, and invasion and by reducing cell sensitivity to anticancer drugs." (PMID 36376274, 2022). "It was reported that GALNT14 was overexpressed in more than 30% of samples from various human malignant tumors." (PMID 36405691, 2022). "Recent studies revealed that GALNT14, which is involved in various biological functions, has abnormal expression in various cancers." (PMID 36077753, 2022). "Approximately 30% of the samples from various human malignancies show GALNT14 overexpression, and GALNT14 affects the O-glycosylation of death receptors in cancer cells and modulates sensitivity to cancer therapy." (PMID 36077753, 2022). "Treatment of cancer cells with GALNT14 siRNA reduced the sensitivity of cells to TRAIL-induced apoptosis." (PMID 34069424, 2021).
cancer (continued). "Recent studies have demonstrated that one of the family’s members, GALNT14, is aberrantly expressed in multiple cancers and involved in a variety of biological functions." (PMID 32098271, 2020). "Here, we summarized the current knowledge of GALNT14 in various cancers, particularly focusing on its role as a biomarker." (PMID 32098271, 2020). "The functions of GALNT14 in various cancers have been studied, including the alteration of apoptotic signaling, change of tissue invasiveness, and modulation of migration properties." (PMID 32098271, 2020). "This review summarizes our current knowledge of GALNT14 functions in various tumors, so as to provide insight into its predictive values in the therapeutic outcomes of cancers." (PMID 32098271, 2020). "Further studies are still needed to provide the missing mechanisms regarding the links between the genotypes and expression levels, as well as other GALNT14-involved microenvironmental elements that can modulate cancer behaviors." (PMID 32098271, 2020). "The expression level of GALNT14 as well as its SNP genotype can be used to predict clinical outcomes in various types of cancer." (PMID 32098271, 2020). "This review summarizes the structural features of GANLT14, its functional roles, and the predictive values of GALNT14 genotypes and enzyme levels in multiple cancers receiving distinct anticancer therapies." (PMID 32098271, 2020). "The inhibitory effect of lung-derived bone morphogenetic proteins (BMPs) on cancer self-renewal was overcome by GALNT14, which facilitated metastasis initiation within the lung microenvironment." (PMID 32098271, 2020). "GALNT14 is important during embryonal development, and its relevance in cancer and cancer therapy is being investigated." (PMID 30632303, 2019). "First, tumors with GALNT14 “TT” genotype have more aggressive cancer invasion property during oncogenesis." (PMID 27124048, 2016). "One report identified high expression of the O-glycosylation enzyme GALNT14 as a signature of TRAIL sensitivity in cancer cells." (PMID 24948009, 2014). "GALNT14 initiates O-glycosylation, influencing cancer cell proliferation, migration, and metastasis, with its expression levels and SNP genotypes predictive of cancer outcomes." (PMID 39981259, 2025). "Notably, seven UReg genes (GALNT14, KIAA0040, EPB41L1, ZNF469, BLNK, AK7, and WSCD1) are associated with the progression of various cancers in humans." (PMID 40241800, 2025). "These cumulative findings strongly suggest that genetic variations within or near the GALNT14 gene may wield substantial effects on cancer behavior, thereby influencing therapeutic responses." (PMID 38928347, 2024). "The levels of GALNT14 across cancers were examined using the TIMER database." (PMID 38024474, 2023). "However, some studies have shown that high GALNT14 expression induces chemoresistance in cancer cells." (PMID 36077753, 2022). "The expression of GALNT14 correlated with Apo2L/TRAIL sensitivity in several cancer types." (PMID 34069424, 2021). "GALNT14 also possesses other functions less relevant to cancer." (PMID 34829768, 2021). "Similarly, levels of DNA methylation in RASSF2, SOX5, GALNT14 and miR-34b/c, four cancer-related genes, were strikingly higher in lesions located in the proximal colon (from the cecum to the descending colon) than in those in more distal subsites." (PMID 27145369, 2016). "Of note, some of the identified drugs are anti-cancer agents that inhibit RNA formation, such as floxuridine, oxaliplatin, and cisplatin, which are related to ABCC5 and GALNT14." (PMID 37478211, 2023). "It was revealed that several top up‐regulated genes such as KANK1, GALNT14, TMEM98, and PTPN3 and top down‐regulated genes such as PITX2, SNCA, and EPHA7 play key roles in cancer progression and chemotherapy response." (PMID 37937323, 2023). "Certain putative substrates of GALNT14 in other (not HCC) cancer cells have been proposed, including MUC13, EFEMP2, and DR5." (PMID 36376274, 2022).
cancer (continued). "The enzyme polypeptide GalNAc-transferase (GALNT14) appears to be mainly responsible for O-glycosylation, and knockdown of GALNT14 with siRNA reduced TRAIL sensitivity and TRAIL-induced apoptosis, while overexpression increased sensitivity in several cancer cell types." (PMID 34069424, 2021). "Previous studies of the predictive role of the GALNT14-rs9679162 SNP showed that in HCC and esophageal cancer (“carcinoma”), patients with the “TT” genotype have a better prognosis, whereas in other cancers (“adenocarcinoma”), patients with the “GG” genotype have better outcomes." (PMID 32098271, 2020). "Consistently, they demonstrated that GALNT14 knockdown decreased ligand-induced receptor clustering, with subsequent inhibition of the extrinsic apoptotic signaling, highlighting the potential use of GALNT14 as a predictive biomarker for Apo2L/TRAIL-based cancer therapy." (PMID 34440905, 2021).
tumor (20 papers, 2010 to 2025). "The risk score of all tumor samples was counted as follows: Risk score = (0.974* B4GALT3) + (0.418* PYGL) + (0.195* GALNT14) + (−0.413* FUT2) + (−0.886* GALNT16)." (PMID 38244579, 2024). "On the contrary, the GALNT14 mutation was further observed in tumor DNAs of two heterozygous NB twins and in both somatic and germline DNA from one sporadic NB patient." (PMID 26309160, 2015). "GALNT14 may also cause abundant post-translational modifications, such as glycosylation, which is closely related to tumor growth and metastasis as well as resistance to chemotherapy." (PMID 32733355, 2020). "Interestingly, primary tumours with high GALNT14 expression exhibited a significant association with decreased lung metastasis-free survival (MFS), but not with brain or bone MFS." (PMID 27982029, 2016). "The expression levels of key glycosyltransferases, such as B3GNT3, ALG3, and GALNT14, along with tumor GAG content and proteoglycan expression patterns, can guide patient stratification and therapeutic decision-making." (PMID 41008983, 2025). "In the multivariate analysis, all four factors were independent predictors of PFS: GALNT14-rs62139523 “A/G” genotype (p = 0.006), larger tumor diameter (p = 0.003), lower T stage (pT1 to pT3) (p = 0.004), and lower circulating CEA levels (p < 0.001)." (PMID 38928347, 2024). "Overview of the expression intensity (weak, moderate, strong) of GALNT14 in tumor cells dependent on the Gleason score." (PMID 37671061, 2023). "Expression in tumor tissue ranged from weak to moderate, with GALNT14 predominantly localized in perinuclear granular structures." (PMID 37671061, 2023). "Adjacent normal tissue shows intact glandular tissue with a typical weak GALNT14 signal, whereas tumor tissue shows a high number of GALNT14-positive cells with large nuclei." (PMID 37671061, 2023). "Our study showed that patients with GALNT14 “TT” genotype had a higher rate to develop tumor invasion (T4 stage) and thus have an unfavorable OS." (PMID 27124048, 2016). "GALNT14 staining has primarily a spotted appearance near the nuclei of tumor cells." (PMID 37671061, 2023). "Similarly, the frequency of GALNT14 upregulation was higher in the tumor tissues in the OPSCC patients who died after radiotherapy, or in the overall survival group." (PMID 36077753, 2022). "This suggests that the predictive potential of the GALNT14-rs62139523 “A/G” genotype holds true in most subgroups, except for those with age < 58 years old, CEA ≤ 2.5 ng/mL, tumor diameter > 44.0 mm, and tumor free margin ≥ 50 mm." (PMID 38928347, 2024). "After determining the tumor cells by desmin, marking intact glandular tissue with cytokeratin 7 (CK7) and excluding macrophages by CD68, the distribution and localization of GALNT14 was investigated." (PMID 37671061, 2023). "In the present study, we found that lower expression of GALNT14 was associated with a worse PFS, implying that GALNT14 may play a tumor suppressor role in HCC, but the molecular mechanisms of GALNT14 in predicting survival of HCC patients need to be further investigated." (PMID 38151984, 2023). "However, the relationships between the GALNT14 SNPs, the enzyme expressions, and the tumor behaviors have not been fully unveiled." (PMID 32098271, 2020). "However, we did not observe changes in TRAIL sensitivity upon the ectopic expression of GALNT14 in 231-Par cells (unpublished data), which is consistent with other studies indicating that the GALNT14-mediated increase in TRAIL sensitivity is a tumour type-dependent phenomenon." (PMID 27982029, 2016). "Interestingly, the expression levels of GALNT14 were lower in tumor tissues, and higher expression levels of GALNT14 were associated with a better progression‐free survival (PFS), but the correlations between GALNT14 expression levels and HCC OS were not significant." (PMID 38151984, 2023).
infection (1 paper, 2023). The state of being infected such as from the introduction of a foreign agent such as serum, vaccine, antigenic substance or organism. "We noted a high level expression of RRM2, MYBL2, and some other genes such as GALNT14, CENPU, ACOXL, and U2 at 0 weeks during active phase of infection, which were downregulated at 8 weeks after therapy." (PMID 37434783, 2023).
neurological disorders (1 paper, 2025). "We identified 7 GALNT14 LOF variants among 9,012 well-curated exomes from self-declared healthy individuals and participants from genetic studies of neurological disorders from Columbia University (allele frequency 0.0004)." (PMID 40153534, 2025).
GALNT14 also shares sentences with these, for which no sentence is quoted: pancreatic carcinoma (6 papers); esophageal squamous cell carcinoma (3); pancreas cancer (2); benign prostatic hyperplasia (1); bladder cancer (1); bladder urothelial carcinoma (1); celiac disease (1); diffuse large B-cell lymphoma (1); esophageal cancer (1); head and neck squamous cell carcinoma (1); hepatitis B (1); IgA nephropathy (1); inflammation (1); kidney cancer (1); lobular breast cancer (1); lung squamous cell carcinoma (1); lymphoid cancers (1); metastasis (1); metastatic tumor (1); microhematuria (1); pancreatic ductal adenocarcinoma (1); rhabdomyosarcoma of the prostate (1); rheumatoid arthritis (1); skin cancer (1); uterine corpus endometrial carcinoma (1).